MIMS2 (mitochondrial inner membrane scaffold 2)
Description:
Mitochondrial inner membrane adapter protein essential for terminal erythroid differentiation and heme biosynthesis. Facilitates formation of an oligomeric mitochondrial iron transport complex required for iron acquisition during heme synthesis, although it does not function as a direct iron transporter (By similarity). Directly interacts with terminal heme synthesis enzymes PPOX and FECH to enhance ferrochelatase activity and couple iron import with heme synthesis (By similarity). Regulates mitochondrial energy metabolism through interaction with ATP synthase subunits.
Synonyms: C20orf108; FAM210B; dJ1167H4.1; DKFZP434A1114; 5A3
Tractability: Antibody: UniProt predicts a signal peptide or a membrane-spanning region; the Human Protein Atlas places it where antibodies can reach. PROTAC: its protein half-life has been measured.
Gene: Protein-coding gene on chromosome 20 (56,358,974 to 56,368,663, forward strand). Ensembl gene ENSG00000124098.
Subcellular location: Mitochondrion inner membrane
Subcellular location (Human Protein Atlas): Cytosol; Plasma membrane
Gene Ontology:
Molecular function: protein binding; protein-macromolecule adaptor activity
Biological process: cellular response to estradiol stimulus; erythrocyte differentiation; positive regulation of erythrocyte differentiation; proton motive force-driven mitochondrial ATP synthesis; positive regulation of heme biosynthetic process
Cellular component: membrane; mitochondrial outer membrane; mitochondrion; mitochondrial inner membrane
Genetic constraint (gnomAD): Loss-of-function variants: 11 observed, 13.91 expected, observed/expected ratio (o/e) 0.79, 90% interval 0.5 to 1.31. The synonymous counts are far from expectation, so gnomAD's model fits this gene poorly and the ratio says little. Missense variants: 229 observed, 217.64 expected, observed/expected ratio (o/e) 1.05, 90% interval 0.94 to 1.17. Synonymous variants: 113 observed, 87.95 expected, observed/expected ratio (o/e) 1.28, 90% interval 1.1 to 1.5.
Homologues: Orthologues: chimpanzee FAM210B (98% identical), macaque FAM210B (95% identical), dog FAM210B (82% identical), pig FAM210B (80% identical), guinea pig FAM210B (77% identical), mouse Fam210b (76% identical), rat Fam210b (76% identical), tropical clawed frog fam210b (47% identical), zebrafish fam210b (44% identical), Drosophila melanogaster CG17508 (36% identical), Drosophila melanogaster CG15403 (33% identical). Paralogues in human: MIMS1 (23% identical).
Diseases named in the same sentence as MIMS2 in open-access papers:
MIMS2 is named in the same sentence as 20 diseases in open-access papers, as found by Europe PMC text mining. Sharing a sentence is not in itself a finding about the gene and the disease.
MIMS2 shares sentences with these, for which no sentence is quoted: tumor (5 papers); breast carcinoma (3); cancer (3); hepatocellular carcinoma (3); ovarian carcinoma (3); lung adenocarcinoma (2); lung carcinoma (2); anemia (1); asthma (1); Autoimmunity (1); cervical cancer (1); colitis (1); colon adenocarcinoma (1); glioma (1); immune dysfunction (1); lentivirus infection (1); liver cancer (1); lupus (1); metastatic tumors (1); Splenomegaly (1).